H2AX (H2A.X variant histone)
Diseases named in the same sentence as H2AX in open-access papers (continued):
Sharing a sentence is not in itself a finding about the gene and the disease.
tumor (continued). "HCV also impairs a tumor suppressor substrate histone H2AX, when phosphorylated (γ-H2Ax) acts as a DNA repair factor recruitment platform to sites of damage, inhibition of γ-H2Ax by HCV can disrupt repair, contributing to hepatocarcinogenesis." (PMID 39608222, 2024). "In human tumours, a robust positive correlation was discerned between NCAPH expression and proliferation markers (Ki67) or genomic instability markers (H2AX and CHEK1)." (PMID 38344872, 2024). "In paraffin‐embedded tissue sections, the expression of Ki-67 in tumor tissues of the L3MBTL1 knockdown plus Osimertinib group was significantly lower compared to other groups, while the expression of γ-H2AX and 53BP1 increased." (PMID 39231972, 2024). "Consistent with in vitro results, S phase arrest (cyclin E accumulation), upregulated DNA damage (gamma-H2AX foci), and apoptotic cells (cleaved caspase-3) were observed in JIMT-1 tumor tissues in vivo at the endpoint." (PMID 37596639, 2023). "At the endpoint, the levels of Ki67, p-H2AX, cleaved-caspase 3, cleaved-PARP, p-JNK, CV-B5/F, and HMGB1 were further examined in subcutaneous xenograft tumor sections by IHC." (PMID 37743418, 2023). "To determine whether RHOJ inhibits EMT tumour cells apoptosis by promoting DNA repair and/or replicative tolerance to damaged DNA, as suggested by the proteomic data, we first investigated the level of histone 2A.X phosphorylated at Ser139 (γ-H2AX), a mark of DNA damage after chemotherapy." (PMID 36949199, 2023). "Immunohistochemical analysis revealed that the expression of γ-H2AX was significantly elevated and the percentage of Ki67-positive cells was significantly decreased in SENP5 knockdown tumor cells after irradiation." (PMID 37684630, 2023). "The ability of Dbait to mimic DNADSBs and activate damage signaling kinase activity was confirmed by the analysis of γ-H2AX, PARP in tumor cells." (PMID 36873373, 2023). "When testing the expression levels of γH2AX in tumor tissues of mice receiving combined use of ZCCHC4-siRNA and OXA, we found that combo-treatment markedly increased phosphorylation levels of H2AX in tumors." (PMID 35853866, 2022). "In our research, the silencing of LINC01419 was accompanied by an increase in γ-H2AX, implying increased DNA damage, suggesting that the upregulated LINC01419 in HCC promotes tumor progression by maintaining genomic stability." (PMID 35903292, 2022). "Mechanically, our data validated that SNHG17 can sponge miR-328-3p through acting as a ceRNA and then elevate H2AX expression levels, drive RCC tumor progression." (PMID 34497156, 2021). "In this trial, post treatment tumor biopsies demonstrated a decrease in p-CDC2 and an increase in γ-H2AX which is consistent with our observations preclinically." (PMID 32204315, 2020). "In the current investigation, levels of DNA damage, as measured by γ-H2AX significantly increased in the tumors of LC-COPD, suggesting that severe injury of the DNA took place in the tumor cells of these patients." (PMID 33187221, 2020). "Tumor tissues from mice treated with IR and β-lap demonstrated enhanced PAR and gamma-H2AX (pS139-H2AX, surrogate marker for DSBs) level compared with monotherapy, as well as decreased NAD+ and ATP levels." (PMID 32974194, 2020). "We found that γ-H2AX and PUMA expression level was less increase in tumor sections derived from sh-survivin expressing cells than those from sh-control cells, but γ-H2AX and PUMA expression levels were further increased after IR." (PMID 31959045, 2020). "Multi-parametric staining was performed to identify γ-H2AX (red), pimonidazole (green) and DAPI (blue) in irradiated and unirradiated tumours harvested at 2 h, 3 and 10 days post-irradiation." (PMID 31109312, 2019).
tumor (continued). "Higher expression levels of stem/progenitor cell factors, such as Bmi1, 8-nitroguanine, DNA damage response (DDR) proteins (phosphorylated ATM and γ-H2AX), and manganese-SOD were higher in CD133+ tumor tissues than in CD133- tumor tissues." (PMID 31450710, 2019). "A significantly higher number of gamma-H2AX positive cells were seen in the primary tumor tissue of the H-RT and H-RT+L-TBI group compared to the L-TBI and control group, while H-RT induced significantly more gamma-H2AX foci compared to H-RT+L-TBI (P < 0.05)." (PMID 30873170, 2019). "The aim of the current study was to evaluate the potential value of phosphorylated H2AX (γH2AX) and ATM (pATM) in assessing 12C6+ radiosensitivity of tumour cells." (PMID 28450809, 2017). "Assessment of the aggravated DNA damage induced by alkylating chemotherapy in the combination demonstrates that more tumor tissue is affected by administration of TMZ, as pointed out by the increase of phospho-H2aX histone complexes." (PMID 28450700, 2017). "The percentage of HSCs co-expressing γ-H2AX and α-SMA was also higher in non-tumor regions of SH-HCCs than those of C-HCCs (7.6 ±7.01% vs. 3.8 ± 3.16%, P = 0.023)." (PMID 28273155, 2017). "Quantification of PCNA-, γ-H2AX- and TUNEL-positive cells showed that tumor cell proliferation is significantly increased in tumors isolated from Sesn2-/- mice, while DNA damage and apoptosis were not significantly altered by the loss of Sestrin2." (PMID 26913956, 2016). "We compared the expression of γ-H2AX and 53BP1 foci in the blood lymphocytes of RC patients with different UICC tumor stages." (PMID 26541290, 2015). "γ-H2AX levels were found to be low inthe tumor tissues from vehicle treated mice whereas in the tumor tissues fromSQDG treated mice γ-H2AX levels were increased at intermediatelevels,suggesting induction of apoptotic DNA damage in the SQDG treated tumor cells." (PMID 26189912, 2015). "Consistent with our observation in xenograft tumours, UVRAGFS expression resulted in a significant increase of γ-H2AX foci and levels in SW480 CRC cells." (PMID 26234763, 2015). "The improvement in survival was associated with a marked in vivo depletion in ATR, CHK1 and RAD52, but induction of γ-H2AX, cleaved Caspase 3 and BIM in the engrafted tumor cells following 1 week of treatment with the combination." (PMID 25026298, 2014). "Inhibition of γ-H2AX through interference with upstream kinase activities using caffeine, wortmannin and LY294002 resulted in significantly increased tumour cell radiosensitivity." (PMID 25487737, 2014). "Image cytometry was performed on 469 of the 908 cancers: for γ-H2AX, 385 tumours with both IHC and ploidy analysis were successfully analysed; for ATM, 394 tumours were studied; and for Ku70, 204 tumours were analysed." (PMID 23154512, 2012). "However, while both the tumor and hair bulb contain replicating cells, those of the tumor may have genetic alterations that make their responses to a particular agent different than that of normal replicating cells, both in terms of γ-H2AX foci formation and cell survival." (PMID 21325706, 2011). "We show that KU-55933 is effective in hESCs at lower concentrations typically used to block the DDR in tumor cell lines since radiation-induced CHK2 and H2AX phosphorylation was inhibited." (PMID 20368801, 2010). "Also, increased expression of γ-H2AX, p-ATR, RPA32, CHK1, and RAD51 were noted in tumour tissues, as well as a decrease in phosphorylation of the CHK1 signalling molecule (p-chk1)." (PMID 41228271, 2025). "The formation of γ‐H2AX foci was notably enhanced in irradiated 4T1 cells pretreated with exogenous TGF‐β1, suggesting that exogenous TGF‐β1 facilitated DNA damage repair in tumor cells, thereby contributing to radioresistance." (PMID 40470716, 2025).
tumor (continued). "Moreover, the result of immunofluorescence staining of γ-H2AX, Ki67 and TUNEL showed that restoring RAD51 expression decreases DNA damage and cell apoptosis, and concurrently increases the tumor growth index." (PMID 39865088, 2025). "DNA damage indicated by γ-H2AX staining in tumor sections was not significantly affected by NP@TPEN, but NP@TPEN enhanced NP@DOX-induced DNA damage." (PMID 39507258, 2024). "Similarly, we found that γ-H2AX, a sensitive molecular marker of DNA damage, was highly expressed in PTEN-null EO771 tumor cells, but it was inhibited by PTEN-L treatment." (PMID 38730468, 2024). "Additionally, the expression of Ku70 and p‐DNA PKcs was suppressed, and DNA damage markers (γ‐H2AX and p‐ATM) accumulated in tumours from Hmga1flox/floxK14 mice." (PMID 39690136, 2024). "As a result, H2AX loss restores replication fork stability and increases chemoresistance in BRCA1/2-deficient tumour cells without restoring homology-directed DNA repair, as highlighted by the lack of DNA damage-induced RAD51 foci." (PMID 38789420, 2024). "The DNA damage as measured using the marker γ-H2AX within the cells was significantly higher (133%) in cancer specimens of tumor-bearing mice treated with rucaparib than in non-treated animals." (PMID 36768904, 2023). "γH2AX is formed by phosphorylation of H2AX in the conserved region at the C-terminus of serine-139 after DNA double-strand break, and histone H2AX plays an important role in DDR repair, cell cycle checkpoint regulation, maintenance of genomic stability, and tumor suppression." (PMID 37547297, 2023). "The immunofluorescence staining for γ-H2AX was dramatically increased in the tumor surface in ApcMin/+NHE3−/− mice, with no discernable signal in other genotypes." (PMID 36042372, 2022). "Although the high γ-H2AX expressers assessed by IF were not related to tumor location or size, these tumors exhibited significantly higher mitotic activity (p < 0.001)." (PMID 35406559, 2022). "H2AX, which can be regulated by SNHG17, also plays an essential role in tumor angiogenesis." (PMID 36185210, 2022). "Expression of phosphorylated H2AX at position Ser139 peaked after 30 min up to 2 h of IR-induced DNA damage and subsequently diminished after 6 h in both SUIT2-028 and PDAC3 cells, consistent with previous studies in other tumor cell lines." (PMID 35740699, 2022). "We confirmed on-target drug activity in vivo at these pharmacologically relevant dosages using TOP2cc formation and γ-H2AX as pharmacodynamic markers, interrogated using a RADAR assay, and immunoblotting respectively, using PDX tumor tissue harvested from CX-5461 treated mice." (PMID 34753908, 2021). "HEY cells that are transfected with APOBEC3A were almost stained by the dye of anti-H2Ax antibody, suggesting that APOBEC3A could contribute to the DNA damage in tumor cells thereby playing a role of depressing tumor development." (PMID 34745121, 2021). "Whether for tumor HCT-116 cells or for normal dermal fibroblasts, cisplatin and bleomycin were genotoxic as revealed by induction of the phosphorylation of histone H2AX, a biomarker of global DNA damage." (PMID 32059457, 2020). "Moreover, inhibition of AKT-signaling attenuated co-localization between Rad51 and γ-H2AX foci after Dox treatment, thus suggesting a failure in the recruitment of Rad51 to DSBs in AKT-inhibited tumor cells after Dox treatment." (PMID 33266502, 2020). "Interestingly, γ-H2AX was sustained at high levels in all three BRCA2 monoallelic and biallelic mutant tumor cell lines even after MMC removal but returned to baseline phosphorylation status in wild-type SNU-216 cells during the same time frame." (PMID 32980867, 2020). "TUNEL and gamma-H2AX staining showed that H-RT alone and L-TBI+H-RT could both inhibit primary tumor growth by inducing apoptosis and DNA damage, while the combination treatment induced less apoptosis and DNA damage than H-RT alone." (PMID 30873170, 2019).
tumor (continued). "The previous in vivo experiment proved that the 211At-trastuzumab concentrated in the tumor (i.e., HER2 distribution) correlates to the double-strand break distribution by the γ-H2AX observation, indicating that the 211At-trastuzumab concentration causes the lethal damage to cancer cells." (PMID 30291193, 2019). "Moreover, DTLL induced an increase in phosphorylated γ‐H2AX more than LDM alone, confirming that DTLL inhibited tumor growth much more significantly than LDM." (PMID 30681288, 2019). "Decreased tumor cell density and increased nuclear size were seen when we increased the dose from 16 to 24 Gy, but not in γ-H2AX intensities or MRI tumor volume." (PMID 29859114, 2018). "The induction of DNA double-strand breaks (DSBs) was analyzed by the expression of phosphorylated histone H2AX, i.e. γH2AX, after irradiation of tumor cells, either non-treated or pretreated with inhibitors." (PMID 30647839, 2018). "This higher amount of phosphorylated γ-H2AX is independent of the increase in the size of the tumor nuclei that we also observed because we have quantified γ-H2AX intensity per unit nuclei area." (PMID 29859114, 2018). "Sustained induction of γ-H2AX by the combination of either SB939 or 1179.4b and low-dose radiation (1 Gy) indicates that extensive DNA damage occurs under those conditions and contributes to the anti-tumour effect of SB939 and 1179.4b." (PMID 29784888, 2018). "We show that H2AX decrease following chemotherapy can sensitize TNBC cells to chemotherapy and we establish, for the first time, the relationship between H2AX and NRF2 regulation in tumours." (PMID 27006338, 2016). "No significant change in tumor perfusion or nuclear γ -H2AX was observed in SU.86.86 tumors, TH-302 resistant." (PMID 27227903, 2016). "The induction of DNA double-strand breaks (DSBs), detected by the expression of phosphorylated histone H2AX, was measured 30 min and 24 h after irradiation of tumor cells, non-treated or pre-treated with inhibitors." (PMID 27224913, 2016). "The IHC data indicated that the higher expression levels of γ-H2AX and LC3-II in hinokitiol-exposed mice might suppress tumor progression, resulting in the inhibition of tumor growth." (PMID 25105411, 2014). "Since phosphorylated γ-H2AX, cleaved casepase-3, and cleaved PARP were dramatically increased by KML001, the synergistic effects would be mediated by increased DNA damage and subsequent tumor cell apoptosis." (PMID 25295271, 2014). "Tumor stages DCIS, T1 and T2 exhibited similar levels of expression of both γ-H2AX and 53BP1." (PMID 23617930, 2013). "In contrast, tumor cells pre-treated with AG1024, Erlotinib, or both showed a delayed H2AX phosphorylation peak at 4 hour, and continuous H2AX phosphorylation till 24 h after irradiation, suggesting impairment of DSB repair after AG1024 and Erlotinib treatment." (PMID 23950876, 2013). "We have shown before that constitutive DNA damage signaling represented by H2AX-Ser139 phosphorylation and ATM activation in untreated normal and tumor cells is a reporter of the persistent DNA replication stress induced by endogenous oxidants, the by-products of aerobic respiration." (PMID 22067284, 2011). "The present data demonstrate that exposure of either normal, mitogenically activated lymphocytes, or tumor cell lines (A549, TK6) to metformin leads to a decrease in the level of constitutive phosphorylation of H2AX on Ser139 and constitutive activation of ATM." (PMID 22067284, 2011). "The induction of DNA DSBs, as analysed by the expression of phosphorylated histone H2AX, was measured 30 min, and 24 and 48 h after irradiation of tumour cells, non-treated or pretreated with Hsp90 inhibitors." (PMID 20502461, 2010).
tumor (continued). "Additionally, an IHC assay was employed to assess the levels of Ki67 and γ-H2AX, markers of proliferation and DNA damage, in tumor tissues with or without flavokawain C treatment." (PMID 38460052, 2024). "However, the number of tumor cells positive for Υ-H2AX, a marker of DNA damage was similar in both mice (data not shown)." (PMID 38253636, 2024). "However, phosphorylation of histone 2A.X at Ser 139 (γ-H2AX) was significantly increased after chemotherapy in RHOJ-KO EMT tumor cells compared with WT EMT tumor cells, suggesting that RHOJ prevents DNA damage accumulation in EMT tumor cells." (PMID 37779170, 2023). "Notably, BP tumor cells responded to olaparib with an increase of γ-H2AX, which was significantly reduced by CM from TEMs, but not control BMDMs." (PMID 35641483, 2022). "Co-localization studies revealed that many of the DNA damage sites that are occupied by γ-H2AX did not co-localize with pNPM1 to efficiently repair all the damaged sites, which could in turn lead to tumor cell death." (PMID 36371529, 2022). "Finally, we examined the expression of γ-H2AX, LC3, and Ac-H3 in the A549 tumor." (PMID 34321364, 2021). "Our in vivo data showed that this combination also inhibited the tumor growth and immunoblotting also showed that the expression of apoptotic markers, such as the cleavages of PARP and Caspase 3, as well as DNA damage markers (γ-H2AX) were increased when combining oxaliplatin and SAHA." (PMID 33994851, 2021). "Furthermore, the proportion of γ-H2AX-positive cells was similar in DesPro and DesPro-TK xenografts with TMZ treatment, indicating that depleting pericytes in pericytelow GBM xenografts had minimal influence on improving the anti-tumor efficacy of TMZ." (PMID 34239070, 2021). "Analysis of tumor lysates from control(M1, M2) and arsenic sulfide-treated(M3, M4) mice showed an obvious decrease in the expression of NFATc3 proteins, and there was a significant increase in RAG1 and γ-H2AX protein levels in the tumors from mice treated with arsenic sulfide." (PMID 31822296, 2019). "Bioluminescence images and IHC also revealed that Fstl1 silencing could not affect the tumor growth and the levels of cleaved caspase-3, γ-H2AX, and MGMT in DIP2A-KD P-GBM2 cells following TMZ treatment." (PMID 30542120, 2019). "The in vivo assay showed that compared with other treatments, PDMP was most effective in inhibiting tumor growth, prolonging survival time, decreasing expression of CD31, CD133, and ALDH1, inducing G1 phase arrest, increasing the apoptosis rate, and in expressing ATM and γ-H2AX." (PMID 29416613, 2018). "Moreover, H2AX phosphorylation by DNA-PK was exclusive to tumour cells, thus indicating sparing of surrounding non-tumourigenic tissue." (PMID 29641431, 2018). "There was an increase in γ-H2AX phosphorylation, an indicator of DNA breaks, as well as a reduction in positive staining for PCNA, a marker for cellular proliferation, in both the lemongrass and the white tea extract-treated groups compared to the control group in the tumor sections." (PMID 29340014, 2017). "ROC curve of γ-H2AX level was used to predict tumor recurrence and non-recurrence after LT." (PMID 25537504, 2015). "In our study, complete ɣ-H2AX target inhibition was observed; however, these data should be interpreted with caution, as the assay was not a direct measure of target inhibition in patients due to target modulation being assessed in blood samples rather than in tumour biopsies." (PMID 38287179, 2024). "No tumour-related deaths were observed in either treatment group, and immunohistochemical analysis of the treatment groups at 1 d and 7 d p.i. showed an increase in γ-H2AX foci in the [225Ac]Ac-polymersomes group, indicating a larger degree of double-stranded breaks." (PMID 31406320, 2019).